BRAF (B-Raf proto-oncogene, serine/threonine kinase)
Diseases named in the same sentence as BRAF in open-access papers (continued):
Sharing a sentence is not in itself a finding about the gene and the disease.
glioma (continued). "In most pilocytic astrocytomas (even after thorough analysis), an activating change in BRAF or other MAPK pathway members is the only genomic change that can be confidently detected, implying that it is the glioma initiation event in this disease." (PMID 29616301, 2018). "Previous studies have shown that BRAF V600E and CDKN2A alterations were less commonly observed in PLGG that did not transform, but more frequently detected in secondary high grade gliomas." (PMID 29152094, 2017). "It has also been reported that combination BRAF inhibition and MEK inhibition prevents MAPK pathway reactivation and an improved reduction in pERK in glioma models." (PMID 28094001, 2017). "In the RMPAlow gliomas, a different set of RTK signaling-related genes including MET (8.9%), EPHA1 (8.9%), EPHB6 (8.9%), EPHB4 (8.3%), BRAF (8.9%), FGF6 (11.9%), FGF23 (11.9%), NTF3 (11.9%), and ANGPT1 (9.5%) were amplified." (PMID 27385209, 2016). "Using this system we previously validated the role of mutant BRAF and canonical MAPK signaling in glioma development and maintenance." (PMID 25821557, 2015). "Genetic alteration of the BRAF gene and subsequent MAPK pathway activation is a frequent molecular event in a subset of human glioma, astrocytoma." (PMID 29061943, 2015). "Although only 15% of canine gliomas harbored a detectable cBRAFV595E, it is of note that ~60% of canine gliomas show copy number gain of the gene, which raises the possibility that increase in BRAF gene dosage may serve as another mechanism for MAPK pathway dysregulation." (PMID 29061943, 2015). "A wildtype BRAF model was excluded from our analyses as it has been shown that in contrast to BRAFV600E cells, PLX4720 promotes wildtype BRAF glioma growth due to transactivation of wild type BRAF." (PMID 26023796, 2015). "Pre-clinical in vivo and in vitro data in BRAF V600E gliomas demonstrate dramatic cooperation between XRT and small molecule inhibitors of BRAF V600E." (PMID 23717811, 2013). "Results from the phase II FIREFLY-1 clinical trial assessing the type-II pan-RAF inhibitor tovorafenib showed high tolerability and strong efficacy in non-Class I BRAF-mutant pediatric low-grade gliomas (pLGG) harboring BRAF structural rearrangements." (PMID 39018217, 2024). "The more appealing targets for H3.3-G34 mutant gliomas are represented by PDGFRA, BRAF, and IDH1." (PMID 39202398, 2024). "Therefore, in recent decades, a lot of researchers have paid attention to the therapeutic roles of BRAF inhibitors and MEK inhibitors (a key inhibitor of the MAPK pathway) in BRAF V600E mutant glioma." (PMID 39172230, 2024). "There is no immune-competent, low-grade glioma model that has a BRAF fusion for preclinical testing." (PMID 39137048, 2024). "The combined BRAF/MEK-inhibitor therapy was first implemented in BRAFV600E-mutant, malignant melanoma (MM), but several groups also reported on patients with BRAFV600E–mutant gliomas or eGB who have responded to MAPKi." (PMID 39107839, 2024). "Pediatric gliomas often harbor BRAF fusions (e.g., KIAA1549-BRAF) that also respond to dabrafenib, though the drug’s efficacy may vary depending on the specific mutation type and tumor microenvironment." (PMID 39654184, 2024). "It was evaluated first in the human phase I trial of adult patients with advanced BRAFV600-mutated solid tumors, including those with an active brain metastasis or primary CNS cancer, regardless of prior BRAF inhibitor use." (PMID 38203795, 2024). "While BRAF alterations are significant and potentially targetable in glioma, the frequency, spectrum, and clinical implications of BRAF alterations in adult glioma have not been previously characterized due to their rarity." (PMID 36854806, 2023). "Given the lack of therapeutic options, the presence of BRAF alterations represents a unique potential for targeted therapy that has, otherwise, not been successful in gliomas." (PMID 37124503, 2023).
glioma (continued). "Targeting BRAFV600E with specific BRAF inhibitors (BRAFi) in monotherapy and in combination with downstream MEK inhibitors (MEKi) led to improved patient outcomes in different cancer entities, including gliomas." (PMID 36698391, 2022). "Some reports suggest no cases of BRAF fusion in a range of low-grade gliomas, whereas other cohorts report the alteration in up to 15% of non-pilocytic low-grade gliomas." (PMID 35436952, 2022). "Furthermore, we reported the main available data about current BRAF and MEK targeted therapies used in pediatric low-grade gliomas (pLLGs), pediatric high-grade gliomas (pHGGs), and other CNS tumors that often present BRAF or MEK mutations." (PMID 36077798, 2022). "BRAF/MEK treatment was terminated and conventionally fractionated radiotherapy with a dose of 2 Gy × 30 was initiated, analogous to treatment for high-grade glioma." (PMID 35198980, 2022). "For this reason, first generation BRAF inhibitors should not be used in glioma which shows this fusion." (PMID 36077798, 2022). "It is interesting to note that in contrast to glioma, KIAA1549-BRAF is the most common BRAF fusion." (PMID 36612279, 2022). "Moreover, additional genetic events, such as ATRX, TERT, and BRAF, which also frequently occur in IDH-mutant glioma, should be considered in future investigations." (PMID 34440884, 2021). "Sequencing analyses revealed that KNS1451 did not harbor glioma-related driver mutations, such as IDH1/2, BRAF, and H3F3A, except for the TERT promoter C250T mutation detected by Sanger sequencing." (PMID 33387197, 2021). "Thus, targeted agents including MEK1/2 (an upstream kinase of MAPK), BRAF, and TRK inhibitors have been evaluated and have demonstrated promising activity in pediatric gliomas." (PMID 34604027, 2021). "In particular, MEK1/2, BRAF, and TRK inhibitors have demonstrated significant promise in pediatric gliomas and extracranial solid tumors harboring these alterations and warrant further investigation in larger trials, as well as clinical consideration when these alterations are present." (PMID 34604027, 2021). "The IDH-wildtype astrocytic glioma classified as low-grade glioma MYB/MYBL1 by methylation profiling, was negative for IDH1/IDH2 and BRAF mutations by sequencing analysis and was 1p/19q non-codeleted." (PMID 33941250, 2021). "Our group demonstrated significant anti-tumor efficacy of PLX4720 (tool compound analog of the BRAFV600E-specific inhibitor vemurafenib) in intracranial xenografts harboring BRAFV600E-mutant gliomas, while showing no efficacy against BRAF-wild type xenografts." (PMID 32523649, 2020). "The first reported trial of a BRAF inhibitor (sorafenib) for pediatric gliomas did not report any secondary skin cancer formation, but instead reported a significant stimulation of glioma tumor growth, which we did not observe in our cohort." (PMID 32523649, 2020). "Moreover, the results showed that glioma-related mutant genes included MGMT (n = 14), IDH1 (n = 8), IDH2 (n = 1), 1p/19q (n = 3), and BRAF (n = 2)." (PMID 32973641, 2020). "The investigation of BRAF inhibitors in glioma animal models showed a higher antitumor treatment efficacy in combination with MEK inhibition, EGFR inhibition or concurrent radiotherapy with longer animal survival compared to BRAF inhibition alone." (PMID 31181803, 2019). "Aggregation of such molecular data sets has enabled novel insights into the pathophysiology of gliomas and has led to the recent introduction of new drugs, which target the MAPK pathway, either indirectly through MEK inhibition or directly with BRAF V600E-specific drugs such as vemurafenib." (PMID 31827999, 2019). "The coexistence of BRAF and TERT promoter aberrations characterizes a subset of aggressive glioma." (PMID 31391125, 2019).
glioma (continued). "Therefore, we established a panel of twelve glioma-derived cell lines with different BRAF and TERT promoter status, containing nine BRAFV600E-mutant and three BRAF wild-type cell models." (PMID 31391125, 2019). "GABPA protein expression, however, was not affected by BRAF-inhibition in double-mutant glioma cells." (PMID 31391125, 2019). "The VE-BASKET study, a non-randomized open label multicohort study of several BRAF V600E mutant central nervous system tumors, showed efficacy of vemurafenib treatment, especially in PXA." (PMID 31181803, 2019). "The high occurrence and impact of BRAF rearrangements in pediatric gliomas, essentially PA, not only open the possibility for better diagnostics but also provides an opportunity for targeted therapy." (PMID 28448514, 2017). "In this connection, we would point out that the “pediatric oligodendrogliomas” (and other low-grade gliomas of the young) reported to date as displaying BRAF and FGFR abnormalities seem not to have been systematically studied for CD34 expression." (PMID 27812792, 2017). "A human BRAF wild-type pediatric glioma cell line (SF188) exhibited no significant response to Db up to concentrations as high as 0.5 μM." (PMID 27713119, 2016). "Moreover, recent studies have demonstrated the antitumor activity of a BRAF inhibitor in preclinical models of BRAFV600E-mutant tumors, including gliomas." (PMID 27529619, 2016). "Histologically, the BRAF-KD tumors resembled highly cellular and invasive gliomas; both possessed a diffuse growth pattern but lacked the necrosis and endothelial hyperplasia typical of grade IV tumors, glioblastoma multiforme (GBM)." (PMID 25821557, 2015). "In certain studies, the KIAA1549:BRAF fusion gene was also found to function through MEK-dependent activation of both MAPK and mTOR pathways and the injection of neural stem cells containing the fusion were sufficient to induce glioma-like lesions in mice." (PMID 25785246, 2015). "In comparison to IDHmut gliomas, IDHwt gliomas have greater activation of receptor tyrosine kinase signaling through EGFR gain, MET gain, and BRAF gain, in addition to increased gains in cell cycle activators and losses of cell cycle inhibitors compared to IDHmut gliomas." (PMID 26091668, 2015). "We found that intracranial infection of newborn N-TVA/Ink4a/Arflox/lox mice with RCASBP(A) viruses containing BRAF-FLVE, KRASG12D or gain of function MEK (MEKGF) in combination with Cre leads to the development of high grade gliomas of various subtypes and morphologies." (PMID 25821557, 2015). "None of the mice infected with RCASBP(A) viruses containing BRAF-KD or Cre alone developed tumors; however, gliomas were detected in 21% (6/29) of mice injected with RCASBP(A) viruses containing BRAF-KD and Cre." (PMID 25821557, 2015). "For highly mutated cancer sites such as colon or stomach, our results confirm a strong association between BRAF mutation and COAD-CIMP but do not show any particular associations with IDH1/2, which have been reported to be causal in gliomas and leukemia." (PMID 26463173, 2015). "In terms of prognosis, the KIAA1549 BRAF fusion has been described as an independent positive prognostic biomarker in low-grade pediatric gliomas, irrespective of tumor type." (PMID 25785246, 2015). "The specificity with which the C-terminus of RAF fuses to these different genes suggests that it is required for tumorigenesis in this context; however, the role of the C-terminal domain of BRAF within the fusions in glioma formation has not been validated." (PMID 25821557, 2015). "Whether resistance to BRAF V600E inhibitors also arises in gliomas, where EGFR and PI3K/mTOR pathways are often over-activated, remains to be seen in neuro-oncology patients treated with BRAF V600E inhibitors." (PMID 23717811, 2013).
glioma (continued). "In pediatric low-grade glioma, consisting of pilocytic astrocytoma and fibrillary astrocytoma, chromosome 7q34 rearrangements result in an in-frame KIAA1549:BRAF fusion gene that possesses constitutive BRAF kinase activity resembling oncogenic BRAF (V600E)." (PMID 24212955, 2011). "Among glioma, the most frequent CNS tumor entity, mutations within canonical histones H3.1 (HIST1H3B/C), H3.2 (HIST2H3C) and non-canonical histone H3.3 (H3F3A) as well as BRAF are well-established markers routinely analyzed in tumor tissue." (PMID 39751690, 2025). "We focused on genes mediating selumetinib sensitivity as potentially druggable dependencies, and the top 2 conserved sensitivity hits were BRAF, a direct effector of Ras with established roles in glioma, and SHOC2, which has not been previously implicated in glioblastoma to our knowledge." (PMID 40985888, 2025). "We assessed whether treatment with a SHP2i would impact the fraction of GTP-bound RAS across five different BRAF V600E mutant glioma lines and saw no change." (PMID 40900823, 2025). "Although there have been attempts at developing BRAF V600E–mutant glioma models, we are not aware of the existence of an immune-competent BRAF fusion PA model in which we could therapeutically test the effects of anti-TIM3 preclinically." (PMID 39137048, 2024). "Additionally, important to note is that KRAS and BRAF do not typically co-occur in gliomas, but a common finding in GBM is aberrant RAS signaling." (PMID 37231247, 2023). "In the third case, BRAF sequencing could not be carried out in an IDH-mutant glioma case, because tumor DNA had already been used up for methylome analysis." (PMID 37553446, 2023). "As part of the VE-BASKET multi-cohort study for non-melanoma cancers, BRAF inhibition with Vemurafenib led to an objective response rate (ORR) of 25% in a cohort of 24 adult patients with relapsed/progressive BRAFV600E mutant gliomas." (PMID 36698391, 2022). "Thus, when feasible, pediatric LGG should be evaluated for potentially targetable alterations, as MEK1/2, BRAF, and TRK inhibitors have demonstrated promising activity in pediatric gliomas and can be considered for patients who have failed upfront chemotherapy." (PMID 34604027, 2021). "Interestingly, we identified a GOPC-ROS1 fusion in an 8-year-old patient whose tumor lacked BRAF alterations and histologically classified as low grade glioma." (PMID 31995621, 2020). "DNA methylation-based analysis of aA_7 showed elevated scores for pilocytic astrocytoma and BRAF-mutant low-grade glioma but could not finally classify the lesion." (PMID 32758285, 2020). "Also implicated in LGG pathogenesis is the BRAF-MAP kinase pathway, but no significant changes in RAF1, BRAF, and MAPK1 methylation were observed in IDH-mutant glioma in comparison with IDH-wildtype." (PMID 27852048, 2017). "MAPK signaling is commonly activated in pediatric low grade gliomas through BRAF fusions suggesting this rather than PI3K signaling may commonly activate mTOR signaling in these tumors." (PMID 27926496, 2017). "Although a body of literature suggests that a small percentage of diffuse astrocytomas, WHO grade II, have BRAF structural rearrangements, the progression to high-grade gliomas that is expected in diffuse astrocytomas is not expected in tumors with BRAF fusions." (PMID 29141672, 2017). "PTPN9 overexpression per se reduces glioma cell proliferation in the absence of BRAF inhibition in our experiments, indicating that PTPN9 may have a global tumor suppressive role." (PMID 26023796, 2015). "Importantly, our preclinical studies using BRAF inhibitor monotherapy revealed that growth inhibition of BRAFV600E glioma was not durable." (PMID 26023796, 2015). "Our study also revealed new cancer types harbouring known fusions (for example, BRAF fusion in rectal adenocarcinoma, FGFR3 fusion in prostate adenocarcinoma, RET fusions in colon adenocarcinoma and invasive breast carcinoma, EGFR–SEPT14 in low-grade glioma, and so on)." (PMID 25204415, 2014).
glioma (continued). "Also of interest, is that a number of common mutations found in some classes of human glial tumors are absent in our PXA cohort, including mutations in IDH1 and IDH2 and that BRAF is not duplicated in PXA." (PMID 21479234, 2011). "Thus we propose that an unknown mechanism exists to relay the signals from p-BRAF to establish the KCNMA1 levels in glioma cells, and that this occurs without the involvement of p-MEK." (PMID 36763212, 2023). "Interestingly, intracranial overexpression of full-length BRAF V600E could not induce glioma formation alone, but a higher-grade glioma was formed with the additional loss of Ink4a/Arf or AKT activation." (PMID 38318325, 2023). "BRAF V600E-mutated PA appears to be associated with an inferior prognosis compared to PA with wild-type BRAF, which may be due to the fact that class I mutations are such strong drivers of ERK signaling and correlate with the relative absence of BRAF fusions in high-grade glioma." (PMID 31466300, 2019). "Low-grade gliomas with duplication of FGFR1 TKD or MYB overexpression show activation of the MAPK/ERK and PI3K pathways, showing expression profiles similar to those of pilocytic astrocytomas with BRAF fusions and suggest that these pathways may represent potentially important therapeutic targets." (PMID 30279357, 2018). "Moreover, IGFBP7 which acts through autocrine/paracrine pathways to inhibit BRAF-MEK-ERK signaling and induce apoptosis, but it is contradictory to some researcher's findings, as they indicated that IGFBP7 was highly overexpressed in glioma tissues, mediateing glioma cell growth, and migration." (PMID 20158915, 2010). "Unlike BRAF fusions, first- and second-generation RAF inhibitors are not effective in RAF1-fused glioma." (PMID 39409964, 2024). "Single-cell sequencing identified an activated and cytotoxic microglia (MG) population designated MG-Act in BRAF-fused, MAPK-activated pilocytic astrocytoma (PA), but not in high-grade gliomas or normal brain." (PMID 39137048, 2024). "Pan-RAF inhibitors provide a new targeted treatment approach for BRAF-altered gliomas whilst not inducing the RAS-dependent paradoxical activation of the MAPK pathway, unlike the type I BRAF inhibitors." (PMID 37886179, 2023). "To date, we have no data about the effective concentration reached by BRAF and MEK inhibitors in glioma patients." (PMID 36686797, 2022). "In this study, we found that the mutant genes in the metastatic brain tumors included ALK, MDM2, ATM, BRCA1, FGFR1, and KRAS, and there were no glioma-related mutant genes (MGMT, IDH1, IDH2, 1p/19q, BRAF, and TERT)." (PMID 32973641, 2020). "Expression of GPR133 was significantly higher in the core (bulk) of IDH wild-type gliomas, when compared to IDH mutant (including both 1p19q codeleted and non-codeleted subgroups) and BRAF mutant tumors." (PMID 32642706, 2020). "These tumors do not typically bear alterations found in pediatric gliomas (MYB, FGFR1, BRAF V600E-mutant) either." (PMID 33059718, 2020). "Using orthogonal strategies of high-dimensional immunofluorescence multiplexing and sc-Seq within the TME, we discovered that targeting TIM3 could potentially benefit patients with BRAF fusion PA and, more broadly, non-high-grade MAPK-activated gliomas." (PMID 39137048, 2024). "The role of vemurafenib in BRAF V600-mutant gliomas has been investigated in the VE-BASKET trial, which evaluated 24 patients (six GBM, five anaplastic astrocytoma, one high grade glioma not otherwise specified, and twelve with other histologies)." (PMID 34359651, 2021).
glioma (continued). "However, in contrast to previous report with U251 (BRAF wild-type) glioma cells, genetic and pharmacological inhibition of Wnt signaling did not affect BRAFV600E glioma cell growth and did not sensitize RGCs to BRAFV600E inhibition." (PMID 27611946, 2017).